RN7SL627P (RNA, 7SL, cytoplasmic 627, pseudogene)
Gene: Miscellaneous RNA gene on chromosome 17 (18,840,618 to 18,840,920, forward strand). Ensembl gene ENSG00000274747.
Homologues: Orthologues: chimpanzee Metazoa_SRP (98% identical). Paralogues in human: Metazoa_SRP (100% identical), Metazoa_SRP (99% identical), RN7SL620P (99% identical), RN7SL1 (85% identical), RN7SL2 (85% identical), RN7SL3 (84% identical), RN7SL786P (82% identical), RN7SL492P (81% identical), RN7SL679P (81% identical), RN7SL296P (81% identical), RN7SL357P (81% identical), RN7SL828P (81% identical), and 703 more.